INS (insulin)
Diseases named in the same sentence as INS in open-access papers (continued):
Sharing a sentence is not in itself a finding about the gene and the disease.
type 2 diabetes (continued). "Type 2 diabetes is considered to result from a collision between genetic predisposition and an affluent environment, which means that type 2 diabetes develops when people no longer can increase their insulin secretion to meet the increased demands imposed by obesity and insulin resistance." (PMID 31161346, 2019). "In addition, Bergman and colleagues showed that C16:0/C16:0, C18:0/C18:0 and total DAG content were higher in the membrane in muscle of patients with type 2 diabetes when comparing to obese subjects and endurance trained athletes, which indicates a role for DAG in insulin resistance." (PMID 30871020, 2019). "However, in patients with type-2 diabetes where beta-cell impairment is significant, physical training does not decrease insulin secretion." (PMID 30971232, 2019). "Whether glucagon counter-regulation to hypoglycemia is affected during DPP-4 inhibition in type 2 diabetes has been studied in drug-naïve subjects, in subjects when a DPP-4 inhibition was added on to insulin therapy, and in elderly subjects with metformin-treated type 2 diabetes." (PMID 31275243, 2019). "The aim of this study was to compare the efficacy and safety of the patch with that of a standard insulin pen for initiating and managing mealtime analog insulin in people with type 2 diabetes not yet achieving the glycemic goal with basal insulin with/without other antihyperglycemic agents." (PMID 31025878, 2019). "We speculate that in some type 2 diabetes patients insulin insensitivity may not uniformly occur in all tissues." (PMID 30652125, 2019). "We used the 2010–2015 MarketScan Commercial Claims and Encounters data examining 72,971 patients with type 2 diabetes aged 18–65 years old who initiated insulin and had filled a prescription for a non-insulin diabetes medication in the 90 days prior to insulin initiation." (PMID 30759121, 2019). "To fill this gap, we used a large dataset representative of commercially insured adults in the United States to conduct a retrospective cohort study characterizing patterns of non-insulin diabetes medication use among patients with type 2 diabetes as they transition to insulin therapy." (PMID 30759121, 2019). "While ethnic differences were present in the non-diabetic state, they were absent in type 2 diabetes, suggesting that by the end of the glucose tolerance spectrum ethnic differences in insulin sensitivity may have dissipated." (PMID 30729259, 2019). "In people with type 2 diabetes, the release of insulin after a meal is slower, no increase is observed as in healthy people, the peak of insulin secretion occurs 90 to 120 min after starting the meal whereas in healthy people it is observed within the first 30 min." (PMID 30871141, 2019). "Insulin mixture therapy has also proved to be an important factor modifying the plasma profile of NGAL, increasing the concentration of this bioactive molecule in the plasma of patients with type 2 diabetes, after 6 months of its use, in relation to the concentration before treatment." (PMID 31195747, 2019). "A practical implication is that in late-onset cases presenting with a clinical picture that is compatible with type 1 diabetes, autoantibody testing might be useful in excluding cases of type 2 diabetes who will not need long-term insulin therapy." (PMID 31438962, 2019). "Conversely, a string of studies conducted in patients with type 2 diabetes opposed a direct effect of insulin on Lp(a) levels because no significant decline in Lp(a) was observed after oral hypoglycemic treatment, despite significant improvement in glucometabolism traits." (PMID 31089476, 2019). "The T allele frequency of BACH2 in the six patients with insulin‐triggered type 1 diabetes (0.75) was found to be significantly higher than that in non‐diabetic control participants and type 2 diabetes patients with and without insulin treatment (P = 0.035, 0.034 and 0.037, respectively)." (PMID 30970177, 2019).
type 2 diabetes (continued). "Similarly, participants with type 2 diabetes using insulin had a nonsignificant decrease in percentage of BG checks greater than 180 mg/dL from 33.5% to 25.9% (P=.43)." (PMID 31593545, 2019). "However, if this state of insulin resistance (IR) is not compensated by an increase in beta-cell insulin secretion, it determines the appearance of GDM and provides a higher risk to develop type 2 diabetes (T2D)." (PMID 31053128, 2019). "Type 2 diabetes patients sometimes have high levels of amisyn in their β-cells, which could explain why they do not release enough insulin." (PMID 31099751, 2019). "Finally, early reduction of circulating follistatin after bariatric surgery predicts the improvement in insulin sensitivity observed later in morbidly obese individuals with and without type 2 diabetes." (PMID 31672146, 2019). "Knockout mice lacking Rab3 or Rab27 both exhibit reduced insulin secretion as a consequence of impaired granule docking at the plasma membrane, consistent with the notion that these proteins are involved in the pathogenesis of type 2 diabetes." (PMID 31533953, 2019). "Our data support a positive regulatory role for both P2Y1 and PKD1, particularly in obese (but nondiabetic) donors, suggesting a role for this pathway in compensatory upregulation of insulin secretion and that disruption of P2Y1‐PKD1 signaling may promote β cell dysfunction in type 2 diabetes." (PMID 31591827, 2019). "As a result of the conducted research, it was proved that plasma concentrations of omentin-1 in patients with type 2 diabetes, before the implementation of insulin therapy, were not statistically significantly different from the concentration of this protein in the control group." (PMID 31195747, 2019). "In addition, we did not measure oxidative stress and GLUT-4 protein levels in insulin sensitive tissues; these factors affect glucose metabolism in type 2 diabetes." (PMID 30621352, 2019). "Potential drugs can be divided into PPAR-γ agonist, β3-AR agonist, insulin sensitizer, insulin, and lipase clearing factor stimulant, acting on signaling pathway including “PPAR signaling pathway”, “adipocytokine signaling pathway”, “insulin signaling pathway”, and “type II diabetes mellitus”." (PMID 31699147, 2019). "While HbA1c improved from baseline to 12-months, it was not statistically significant at any time point for participants with type 1 diabetes, type 2 diabetes, or participants with no insulin usage, whether with type 1 or type 2 diabetes." (PMID 31593545, 2019). "Reduced hepatic insulin sensitivity in metabolic syndromes, such as type 2 diabetes (T2DM) and non-alcoholic fatty liver disease (NAFLD), may result directly from reduced insulin receptor numbers or indirectly from reduced insulin action via post-insulin receptor signalling pathway genes." (PMID 31284538, 2019). "High plasma leptin predicted low insulin sensitivity in a young group of women with recent GDM, suggesting that leptin signaling may be more important than low-grade inflammation as a contributor to type 2 diabetes." (PMID 29951553, 2018). "This study shows that in real-world clinical practice, the linagliptin-basal insulin regimen was as effective and safe as the standard basal-bolus regimen in non-critical patients with type 2 diabetes with mild to moderate hyperglycaemia treated at home without injectable therapies." (PMID 30208631, 2018). "However, while previous studies have investigated and compared CSII, MDI, OHAs, or insulin glargine monotherapy as short-term intensive treatment for people recently diagnosed with type 2 diabetes, basal insulin plus OHAs has not been investigated." (PMID 30420969, 2018). "Thus, the proper animal model for Asian type 2 diabetes needs to be non-obese, have lower insulin secretion capacity, and higher insulin resistance than the non-diabetic rats." (PMID 30041479, 2018). "Changes in diet are important in the control of type 2 diabetes, with/without insulin involvement." (PMID 30510730, 2018).
type 2 diabetes (continued). "Furthermore, one of the four reviews only included patients with type 2 diabetes using insulin, two reviews included both insulin- and non-insulin-dependent patients with type 2 diabetes and one review provided no details on this." (PMID 29940936, 2018). "Ginseng thus has a significant effect on insulin sensitivity and may exert preventive and treatment effects in type 2 diabetes and hyperglycemia in db/db mice despite the absence of a significant effect on weight loss." (PMID 29861768, 2018). "An alternative explanation is that individuals with type 1 diabetes must utilize intensive insulin management techniques, whereas individuals with type 2 diabetes may not." (PMID 30291079, 2018). "An EN formula containing high-protein and low-carbohydrate loads can significantly improve glucose control in subjects with type 2 diabetes in ambulatory settings as evidenced by observed improved glucose control without significant difference in insulin response." (PMID 30158516, 2018). "The combination of freeze-dried aronia, red ginseng, ultraviolet-irradiated shiitake mushroom and nattokinase (AGM; 3.4:4.1:2.4:0.1) was examined to evaluate its effects on insulin resistance, insulin secretion and the gut microbiome in a non-obese type 2 diabetic animal model." (PMID 30041479, 2018). "These biosimilars may be considered as alternative options for non-basal and basal insulin therapy in patients with type 1 and type 2 diabetes." (PMID 29668697, 2018). "How about the insulin sensitivity in non-obese persons with type 2 diabetes?" (PMID 29536426, 2018). "We report herein that incremental dosing of gliclazide MR 60 mg QD over 6 months was well tolerated and led to significant and clinically meaningful HbA1c reductions, as early as 3 months, in individuals with type 2 diabetes, not treated with insulin and with a broad range of baseline HbA1c." (PMID 29651307, 2018). "Indeed, insulinogenic index or its composite with insulin sensitivity (oral disposition index) has been demonstrated to be predictive of type 2 diabetes, independent of fasting plasma glucose in different populations." (PMID 29765987, 2018). "Since the emergence of continuous subcutaneous insulin infusion (CSII) therapy in 19971, CSII has become the potential treatment for type 2 diabetes (T2D)." (PMID 29946148, 2018). "Decrease in myocardial SUR2A could explain negative cardiac events observed in insulin-treated diabetes type 2 patients and shorter lifespan." (PMID 30211323, 2018). "In adults presenting with the disease, unlike children, it may masquerade as type 2 diabetes, since insulin therapy is not always required." (PMID 29619531, 2018). "Furthermore, the genus Collinsella has been associated with increased fasting levels of insulin and HOMA-IR in normoglycaemic pregnancies and is enriched in non-pregnant patients with type 2 diabetes." (PMID 29764499, 2018). "Thus it seems that, even in the presence of plasma protein, gliclazide block is quantitatively sufficient to stimulate insulin secretion and the functional data are in reasonable agreement with the free CSS concentration of drug in the plasma of patients with type 2 diabetes." (PMID 29772022, 2018). "Self-monitoring of blood glucose (SMBG) was more common among type 1 diabetes patients than type 2 diabetes patients (73% vs. 17%, p = p < 0.001), likely influenced by the limited free distribution by MSF of blood glucose meters and testing strips to some patients taking insulin." (PMID 30214472, 2018). "Asians with type 2 diabetes are usually not obese, although they are insulin resistant." (PMID 30041479, 2018). "However, the heritability and impact of first-degree family history (FH) of type 2 diabetes on insulin secretion and action have not been adequately described." (PMID 29274011, 2018).
type 2 diabetes (continued). "Most individuals with type 1 diabetes develop diabetic retinopathy, and a growing number of those with type 2 diabetes now manifest it, with high blood sugar, insulin resistance and a relative lack of insulin for which limited therapies are currently available." (PMID 30094465, 2018). "In multivariate adjusted models, ORs (95% CI) for incident type 2 diabetes for the highest quintile in comparison with the lowest quintile were 9.0 (4.4, 18.5) for FPG, 6.1 (2.9, 12.7) for 2hPG, 3.8 (2.0, 7.2) for HbA1c, 1.9 (0.9, 3.6) for fasting insulin and 2.8 (1.4, 5.6) for HOMA-IR." (PMID 29018885, 2018). "In experimental animals, it has been demonstrated that insulin inhibits cardioprotection afforded by ischaemic preconditioning while in patients with type 2 diabetes, concerns about negative cardiac events when insulin is used as a therapeutic have been raised." (PMID 30211323, 2018). "In conclusion, the HbA1c level closer to 47.5 mmol/mol achieved mainly with insulin-sensitizing agents and lifestyle modification would be a safe glycemic goal for improving the outcome measures of DPN in patients with poorly controlled type 2 diabetes with mild to moderate neuropathy." (PMID 29545773, 2018). "Thus, plasma insulin, which should change during the glucose tolerance test, was not measured in this study, but given that the patients had type 2 diabetes, they will have varying levels of residual insulin production and insulin sensitivity." (PMID 30319819, 2018). "Adults with self-reported type 1 diabetes who did not report insulin use were reclassified as having type 2 diabetes, which might have resulted in misclassification if they actually used insulin but did not report use." (PMID 29596402, 2018). "Interestingly, glucose clamp studies indicated that peripheral insulin resistance was presented similarly in both autoantibody positive and negative patients of clinically diagnosed type 2 diabetes." (PMID 29887833, 2018). "Furthermore, although we adjusted for glycated haemoglobin, the potential confounding of insulin control may also influence variation in RVP between type 1 and type 2 diabetes." (PMID 29500396, 2018). "The intake of higher doses of resveratrol did not affect the circulating levels of glucose, insulin, glycosylated hemoglobin, and glucagon-like peptide-1 in type 2 diabetic patients, as well as glucose tolerance and insulin sensitivity in older glucose-intolerant adults." (PMID 30400297, 2018). "Previous studies comparing insulin degludec/insulin aspart (IDegAsp) with premixed insulin twice daily among insulin users with type 2 diabetes have not thoroughly investigated differences in the glucose variability and psychological evaluations related to insulin regimen changes." (PMID 30127860, 2018). "Higher glucose levels and insulin responses during the OGTT (i.e., 1-h glucose and the shape of the plasma glucose curve) are indeed related to the risk of developing type 2 diabetes, particularly if the 2-h plasma glucose does not return to or below the fasting plasma glucose levels." (PMID 30042734, 2018). "Therefore, the present study was designed to directly compare the PD properties of increasing doses insulin detemir and insulin glargine in severely obese (WHO grade 2 or higher) patients with type 2 diabetes over a 30 hour period in a randomised cross-over design." (PMID 30114246, 2018). "A large European study among people with type 1 diabetes and insulin-treated type 2 diabetes showed that non-severe hypoglycemia may also have a substantial negative impact on energy and mood." (PMID 29347915, 2018). "Type 2 diabetes develops when beta cells are not able to fulfill insulin needs." (PMID 28742858, 2017). "Type 2 diabetes may happen in condition that the body resisted the effects of insulin or there is not enough secretion of insulin." (PMID 28484730, 2017).
type 2 diabetes (continued). "This study will attempt to answer the question of whether structured SMBG provides any benefits to people with poorly controlled type 2 diabetes who are not being treated with insulin." (PMID 28143495, 2017). "Therefore, when insulin resistance occurs (as in obesity and type 2 diabetes) or there is complete absence of endogenous insulin (as in type 1 diabetes) there is relative hyperglucagonaemia." (PMID 28733905, 2017). "However, the benefit of SMBG in insulin naïve type 2 diabetes has not been a consistent finding in the limited number of randomised control trials (RCTs) published to date." (PMID 28143495, 2017). "Although the mechanistic details are far less understood than the insulin/IGF pathway, their importance is gaining impetuous as the amino acid profiles or their metabolic enzymes are altered in several disease conditions, including Type 2 diabetes mellitus (T2DM) and AD." (PMID 28626421, 2017). "Type 2 diabetes is a chronic disease with an adult-onset and mostly is independent of insulin." (PMID 28484730, 2017). "In addition, a study on patients with type 2 diabetes treated with insulin after acute myocardial infarction showed that insulin therapy focusing on postprandial hyperglycemia provided no benefit over insulin treatment with preprandial glucose targets." (PMID 28115994, 2017). "A double-blind, placebo-controlled, randomized clinical trial conducted on patients with type 2 diabetes who did not receive insulin showed that ginger supplementation significantly reduced serum triglyceride and reported a minor beneficial effect on serum glucose." (PMID 28729836, 2017). "Thus, CLW can be a useful herbal treatment for type 2 diabetic patients who are not obese, but have insufficient insulin response to normalize blood glucose when insulin resistant." (PMID 29104217, 2017). "While non-enzymatic glycation of some proteins such as insulin (INS) and hemoglobin A1C is a well-known phenomenon accompanying hyperglycemia in both type 1 and type 2 diabetes, the effects of such glycation on receptor proteins such as the IR have not yet been explored." (PMID 29207492, 2017). "In agreement with our study, a recent meta-analysis showed that 100% fruit juice may have no overall effect on fasting glucose and insulin concentrations in participants with obesity, metabolic syndrome, hypertension, and type 2 diabetes." (PMID 32153825, 2017). "In the Type 2 diabetic rat model induced by HFD and low-dose of STZ, biotin supplementation exerted antioxidant, anti-hyperlipidaemic, anti-inflammatory and anti-hyperglycaemic effects, increasing the level of insulin, probably through modulation of PPAR-γ, IRS-1 and NF-κB proteins." (PMID 28574454, 2017). "Conversely, while in principle E10+ and E11+ should respectively identify individuals with type 1 and type 2 diabetes, we could not exclude that some E10+ patients had insulin-treated type 2 diabetes." (PMID 28314943, 2017). "The lack of response in JO2 to insulin in our subjects with obesity could therefore be interpreted as the early signs of impaired metabolic flexibility which is observed in type-2 diabetes." (PMID 29161316, 2017). "Hyperglycemia, altered insulin action, and increased levels of nonesterified fatty acids may trigger the cardiac phenotype in type 2 diabetes." (PMID 26623724, 2016). "Another study showed that an acute bout of moderate resistance exercise 2.5 hours after meal prevalence of hyperglycemia was reduced by 35% over the next 24 hours in people with impaired glucose tolerance and in those with type 2 diabetes with or without insulin." (PMID 27073714, 2016). "Preoperative 33 patients were using insulin, 35 patients were using oral antidiabetic drugs, 20 patients did not take any medications and were diagnosed to have type 2 diabetes during preoperative assessment; endocrinology prescribed them to use oral antidiabetic drugs." (PMID 27186461, 2016).